CD4 (CD4 molecule)
Diseases named in the same sentence as CD4 in open-access papers (continued):
Sharing a sentence is not in itself a finding about the gene and the disease.
AIDS (continued). "Classification of severe stage of HIV (i.e., AIDS) may also differ between countries, depending on whether only CD4 test results are considered and/or opportunistic illnesses." (PMID 24223724, 2013). "We assessed the impact of TB disease on mortality, loss to follow-up (LTFU) and incident AIDS-defining events (ADEs) through Cox models and CD4 cell and weight response to ART by non-linear mixed models." (PMID 23301015, 2013). "The two mycobacterial species differ in that opportunistic infection by M. avium occurs in advanced stages of AIDS when blood CD4+ T cell counts are lower than 50 per mm3, whereas infection of AIDS patients with M. tuberculosis is not limited to such late stages of the disease." (PMID 24367768, 2013). "HIV-2 infection eventually leads to CD4 depletion, AIDS and death." (PMID 24156513, 2013). "However, exhaustive research on HIV and FIV infections has led to the description of a mechanism inducing AIDS unrelated to CD4+ T-cell counts and involving anergy." (PMID 23917352, 2013). "We populated the model with data on opportunistic infection and mortality risks from the International Epidemiologic Database to Evaluate AIDS (IeDEA), with mean CD4% at birth (42%) and mean CD4% decline (1.4%/month) from the Women and Infants’ Transmission Study (WITS)." (PMID 24349503, 2013). "HAVACS participants were more likely to have had an AIDS-defining event (whether including or excluding CD4<200) prior to HAART initiation and were more likely to be hepatitis C and hepatitis B co-infected at HAART initiation (all p<0.0001)." (PMID 23658717, 2013). "The key player in AIDS pathogenesis and cure is the memory CD4 T-cells." (PMID 24151495, 2013). "Nevertheless, even among patients with advanced AIDS (i.e., absolute CD4+ T cell count <50/mm3) who fail to achieve any substantive immune reconstitution, suppression of HIV replication with ART results in survival rates that far exceed the optimal rates reported before the modern ART era." (PMID 24260125, 2013). "Pharmacological intervention to modulate DRAM in HIV-infected CD4+ T cells may thus help to eliminate viral reservoirs and delay development of clinical AIDS." (PMID 23658518, 2013). "Heterozygotic individuals are not protected against HIV-1 infection but, in most cohort studies, they have been found to have lower viral loads, slower decrease in the CD4+ T cell count and slower progression to AIDS by an additional 2–3 years when compared to CCR5-wild-type individuals." (PMID 24167505, 2013). "Induction of anti-IFNα antibodies by immunization with inactivated IFNα to inhibit progression to AIDS has been investigated in a large multicentre study, and beneficial effects on CD4+ T-cell decline and markers of clinical progression were reported in patients that developed anti-IFNα antibodies." (PMID 24133492, 2013). "VZV was detected in the CSF from one PML patient with AIDS (CD4 cell count, 8 cells/μl)." (PMID 24330281, 2013). "The loss of immune memory repertoires of CD4 T-cell also sets the biggest hurdle to the development of HIV/AIDS vaccine since a damaged CD4 T-cell memory and a CD4 T-cell unhelped CD8 T-cell memory can only lead to a defective vaccine and an aborted vaccination." (PMID 24151495, 2013). "Arising of opportunistic infections and diseases is typical of the Acquired ImmunoDeficiency Syndrome (AIDS) phase, as defined when CD4+ T cell counts drop to <200 cells/μl of blood." (PMID 23577012, 2013). "Memory CD4 T-cells have a pivotal role in HIV/AIDS eradication and cure." (PMID 24151495, 2013). "We analyzed data from HIV-infected individuals who were clinically-eligible for ART between 2001 and 2009 (i.e., a first reported CD4+ <350 cells/uL or AIDS-defining illness) from 14 U.S. cohorts of the North American AIDS Cohort Collaboration on Research and Design (NA-ACCORD)." (PMID 24260137, 2013).
AIDS (continued). "Furthermore, markers of immune activation have been shown to be stronger predictors of progression to AIDS than either the CD4 counts or viral loads." (PMID 24348678, 2013). "We chose to define a normal CD4:CD8 ratio as ≥1.2, based on a previous study that determined this to be the minimum critical value and data from the Multicenter AIDS Cohort Study (MACS) which found that the baseline population CD4:CD8 ratio in HIV uninfected persons was 1.2." (PMID 24204912, 2013). "However, subsequent studies did not observe any impact of anthelminthic treatment and decline in HIV-1 viral loads, lower CD4+ T lymphocytes or faster progression to AIDS." (PMID 23849678, 2013). "AIDS is when the CD4 count, the white blood cells, goes down." (PMID 24023613, 2013). "The remaining nine patients progressed to AIDS, demonstrating CD4+ T-cell counts of <200 cells/μL." (PMID 24319487, 2013). "The median pre-operative CD4 counts in the HIV positive patients were above 200 cells/ml, the cut off below which HIV patients are considered to be at risk of developing AIDS, this signifies that the patients enrolled had good immunity and many hadn’t developed AIDS." (PMID 23442732, 2013). "Therefore; BMI <18.5 kg/m2, disseminated pulmonary TB, lower CD4 count (≤50) and WHO clinical stage 4 of HIV/AIDS were significantly associated with anti-TB drug induced hepatotoxicity from bivariate model analysis." (PMID 23696901, 2013). "Destruction of CD4+T cells by HIV is a marker for the disease progression, which eventually makes the patients vulnerable to opportunistic infections leading to acquired immunodeficiency syndrome (AIDS)." (PMID 23936398, 2013). "However, on a direct cellular basis, the relative frequency of idDC harboring HIV-1 DNA from spleens of AIDS patients ranges from 1/720 to 1/18,000, which is 10–100 times less than CD4+ T cells (range: 1/17 to 1/190)." (PMID 24278768, 2013). "In addition, low CD4 count, high plasma HIV RNA or a history of AIDS-defining diagnosis, have been associated with a higher incidence of CKD." (PMID 23776637, 2013). "Besides, Survival after AIDS diagnosis differed among age at AIDS diagnosis and number of CD4+ T-cells within 6 months at diagnosis (cell/μL)." (PMID 24376638, 2013). "Chinese guidelines of treatment for AIDS proposed that antiretroviral therapy was recommended for asymptomatic patients with a CD4 cell count less than 350 cells/mm3, and antiretroviral therapy should be considered for asymptomatic patients with a CD4 cell count between 350 and 500 cells/mm3." (PMID 23874985, 2013). "An increase in set point of 0.5 log copies/ml decreases the median time to AIDS by 3 years, and the increased CD4 count may prolong the time until HAART has to be reinitiated because of a low CD4 count or disease progression." (PMID 24324793, 2013). "AIDS is established when the CD4+ T-cell count falls <200 cells/ul." (PMID 22427893, 2012). "However, NMC307, NMC716, and NMC842 were recovered from patients at an advanced stage of AIDS with low CD4+ cell counts and high HIV-2 VLs." (PMID 23094081, 2012). "Clinical parameters such as CD-4 cell count, viral load, disease stage, hemoglobin, AST, and ALT levels were used as indicators of ARV treatment efficacy, underlying liver disease and disease progression in the HIV/AIDS patients." (PMID 23133441, 2012). "Moreover, an increase in CD4+ T-cells as well as the progression to AIDS arises with a low possibility." (PMID 22536298, 2012). "At least 20 HIV/AIDS adult patients (average age of38 years) (CD4 lymphocyte counts less than 200/mm3 in 17 patients and most with high viral loads) have been reported as having presented with KD-like clinical signs and symptoms, although none apparently developed documented CA pathology." (PMID 22723916, 2012). "It defines AIDS as all HIV-positive patients with CD4 count <200 cells/mm3 or CD4% < 14%." (PMID 23056931, 2012).
AIDS (continued). "Additionally, the median CD4 cell count of newly diagnosed detainees in EnhanceLink is greater than the median CD4 count at presentation estimated from the North American-AIDS Cohort Collaboration on Research and Design (NA-ACCORD) in 2007 (317 cells/mL)." (PMID 22662177, 2012). "AIDS diagnosis based on < 200 CD4 cells/mm3 of blood and at least one opportunistic infection can serve as another important phenotype for measuring the dynamics of host-virus interactions, but it can take close to a decade to develop even during untreated HIV-1 infection." (PMID 23202454, 2012). "Residual differences in progression to AIDS may also be an artefact of the higher number of CD4 cell measurements taken from SSA cohort participants compared to participants in the resource-rich country cohorts (10 vs. 5 and 4 measurements, respectively)." (PMID 22412867, 2012). "Some of these biological variables may be relatively unique to PLWHA, such as AIDS-related stigma, compromised immune status (low CD4 counts) and increased opportunistic infections." (PMID 23209556, 2012). "Although HIV-1 N strains have not spread extensively, they can cause CD4+ T cell depletion and AIDS." (PMID 23308067, 2012). "DTH responses are a strong in vivo parameter of cell-mediated immunity (CMI) and predict risk of AIDS, independent of the CD4 count and VL." (PMID 22457767, 2012). "AIDS defining illnesses were originally used as clinical indicators of HIV-1 disease progression, however in 1993 the USA widened their definition of AIDS to include a decline in peripheral blood CD4+ T-cell count to less than 200 cells/μl blood or less than 14% of lymphocytes." (PMID 22363409, 2012). "Improved immune function and increased CD4 cell count following HAART could explain the reduction of AIDS progression in case of HAART use in ICU." (PMID 23020962, 2012). "However, contrasting with our and other studies, 80.6% of the ICU admissions were due to AIDS-defining conditions, and all subjects had very low CD4 counts." (PMID 22762133, 2012). "Human immunodeficiency virus HIV-1 is the etiological agent of acquired immunodeficiency syndrome (AIDS), which infects CD4+ lymphocytes in humans." (PMID 23300605, 2012). "As expected, CD4 count at baseline correlated with AIDS-related death." (PMID 22509187, 2012). "Therefore, it is important to explore the anti-viral immunity exerted by CD4+ T cells in order to develop novel vaccines against HIV-1/AIDS." (PMID 23028895, 2012). "Major depressive disorder in people living with HIV/AIDS (PLWHA) is common and may be associated with a number of factors, including AIDS-related stigma, decreased CD4 levels, increased opportunistic infections and sociodemographic variables." (PMID 23209556, 2012). "Moreover, the disappearance of anti-3S antibodies over progression to AIDS is concomitant with CD4 T cell depletion and with an increase in the expression of NKp44L on the surface of these cells." (PMID 22312424, 2012). "A decrease in the total CD4 lymphocyte count below 500/microliter presages the development of clinical AIDS, and a drop below 200/microliter not only defines AIDS, but also indicates a high probability for the development of AIDS-related opportunistic infections and/or neoplasms." (PMID 23077699, 2012). "However, as the peripheral immune organs with their CD4+ helper T cells deteriorate in AIDS, chronic infectious stimuli are apparently unable to maintain the dominating αβ CD8+ IEL population due to lack of T-cell homing to the intestinal mucosa." (PMID 22238587, 2012). "The fact that TB is often diagnosed at higher CD4 cell counts may also explain why the SSA group (which had higher TB rates) progressed to AIDS more rapidly despite their slower CD4 cell decline." (PMID 22412867, 2012).
AIDS (continued). "In conclusion, most of our patients with neurologic manifestations of HIV/AIDS had advanced disease at presentations which was evidenced by: almost all were in stage IV, majority had low CD4 count and most had opportunistic CNS infections as the leading etiologies." (PMID 22490062, 2012). "However, viral load is not integrated specifically into this model and it is only the constant decline in CD4+ T-cells that is interpreted as progression to the AIDS phase." (PMID 23202449, 2012). "The more frequent CD4 testing would allow an AIDS diagnosis to be made earlier." (PMID 22412867, 2012). "In this study, I investigated the strategy of using inoculated SupT1 cells to move infection from HIV-1 X4 strains toward the inoculated cells, which should theoretically prevent infection and depletion of normal CD4+ T cells, preventing the development of AIDS-related pathologies." (PMID 22701517, 2012). "Differences in the incidence of AIDS related mortality could partly be explained by variations in patient demographics including CD4 count and use of effective cART regimens." (PMID 22911841, 2012). "To explore the possibility that NKT lymphocytes can modulate progression to AIDS, we investigated whether NKT frequency prior to SIV infection can affect viral load or CD4+ T lymphocyte loss post SIV infection." (PMID 23028326, 2012). "Cox proportional hazard analysis to AIDS or CD4 cell counts below 200 cells/μl blood." (PMID 22412885, 2012). "Hence the integration of POC CD4 testing into the national AIDS control program would facilitate the better patient management in HIV infection." (PMID 22998738, 2012). "However, it has to be considered that the majority of CD4+ T cells are depleted in the AIDS stage; and a large proportion of patients progressing to AIDS still harbor viruses that use CCR5 for cell entry." (PMID 23035819, 2012). "Data quality can be improved by future prospective studies from Nigeria to clarify the independent associations, if any, between variables such as CD4 and platelet counts, and mortality of hospitalised HIV/AIDS patients in Nigeria, as shown by studies from other parts of Africa." (PMID 23019521, 2012). "Interestingly, two different measures of late presentation are compared: the lab-based measure (CD4+ T-cell count at presentation <350 cells/mmc) and the time-based one (AIDS event within 12 months of initial HIV diagnosis)." (PMID 22191018, 2012). "Event rates in CD4 strata among the 75,336 patients with at least one suppression episode while on cART: event rates per 1,000 y of suppressed viral load (number of events) over time for the primary outcome (a first new AIDS event or death)." (PMID 22448150, 2012). "Lower CD4+ and higher CD38+CD8+% resulted independently associated with AIDS presentation." (PMID 22110905, 2012). "ART was started when CD4% declined to < 15% or AIDS-related events developed." (PMID 23181827, 2012). "Effects of current CD4 count, viral load and haemoglobin and diagnosis of AIDS-defining events (ADEs) after start of combination ART (cART) on death and new ADEs were assessed using Poisson regression, in patient aged ≥18 years within a multi-centre cohort in Thailand." (PMID 22905264, 2012). "As for criterion validity, the WHOQOL-HIV BREF could discriminate patients at different HIV/AIDS stages in Physical, Social, and Environment, and discriminate different CD4 cell count groups in Performance, Physical and Morbidity." (PMID 22911742, 2012). "For this reason, the clinical significance of the differences in CD4 slope reported in our analysis cannot be evaluated – although many cohorts from resource limited settings clearly assessed the relationship between AIDS-related events, non AIDS related events and death and CD4 cells." (PMID 22742573, 2012). "This was the first AIDS defining illness in this patient even though she had very low CD4 counts." (PMID 21320326, 2011).
AIDS (continued). "Aside from changes in IgA secretion, a few authors have suggested that increased deposition of collagen in AIDS patients may also deplete CD4 T cells." (PMID 21739004, 2011). "The dramatic loss of CD4+ T-cells in all mucosal tissue is a hallmark of early HIV infection, which subsequently leads to several local opportunistic infections and contributes to AIDS." (PMID 21481223, 2011). "In fact, the HIV-1/HTLV-1 co-infection posses a great challenge in AIDS follow up tests such as CD4 enumeration related to the prognosis, and the need for implementation of public health control measures, as well clinical protocols focusing on both HIV-1 and HTLV-1 in Mozambique." (PMID 21532745, 2011). "Despite the fact that combined antiretroviral treatment (cART) has made it possible to control HIV infection and extend survival if started with a CD4+ cell count above 200 cells/mm3, a considerable proportion of patients still present with an AIDS-defining condition at diagnosis." (PMID 22043301, 2011). "TB is frequently observed in HIV/AIDS patients with > 200 CD4+ cells/mm3 and might lead to death at an earlier stage of HIV infection." (PMID 21894262, 2011). "The impairment of these functions may have a dramatic effect on the formation and stability of effective anti-HIV immunity beyond the characteristic depletion of CD4 T cells seen in HIV/AIDS." (PMID 21483689, 2011). "In addition, the number of AIDS deaths decreases at the global level by 21% when the eligibility criterion switches to CD4 count <350, with country-level results varying between decreases of 16% and 23%." (PMID 21490782, 2011). "In HIV-1-infected adults, a loss of naïve CD4+ T-cells precedes the loss of T-cell homeostasis and progression to AIDS, and inverted naïve to effector/memory ratios are not always restored upon administration of ART." (PMID 21298072, 2011). "This tropism for one of the human immune system's major immune response modulators is believed to be the main pathophysiologic mechanism leading to AIDS; the result is a critically reduced number of CD4+ cells, which in turn perturbs the intricate CD4-dependent host immune response." (PMID 21559204, 2011). "The transition from HIV to AIDS is marked by a CD4+ T-cell count below 200 cells/μL." (PMID 21687584, 2011). "Here, the contribution of macrophages could be more eminent than in cohorts that study time to progression to AIDS, which might be more T cell dependent, especially since sometimes AIDS is defined by CD4+ T cell counts." (PMID 21364930, 2011). "And in previous studies, macaques intravaginally infected with SHIV162p3 generally do not progress to AIDS, and survival has been associated with preservation or restoration of central memory CD4+ T lymphocytes." (PMID 21464951, 2011). "The impact of viral load (VL) decay and cumulative VL on CD4 recovery and AIDS after highly-active antiretroviral therapy (HAART) is unknown." (PMID 21625477, 2011). "Failure to restore a normal CD4+ count following HAART is associated with increased morbidity due to both AIDS and non-AIDS events, as well as increased mortality." (PMID 21244701, 2011). "There have been significant declines in HIV-related morbidity and mortality since the advent of anti-retroviral therapy (ART) Initiation of ART is based on CD4 cell count or being classified as being in World Health Organisation (WHO) HIV/AIDS clinical stage III or IV." (PMID 21589912, 2011). "Similarly, the definition of "late presenters" has been recently proposed for those persons with a clinical AIDS-defining condition or a number of CD4+ T cells below 350/μL at diagnosis." (PMID 22166160, 2011). "In the univariate analysis of all the factors significantly modifying all-cause mortality the strongest protective effect was observed for cART as well as CD4 metrics, namely nadir, zenith lymphocyte CD4, time with CD4 count above 500 cells/μl and AIDS-free observation." (PMID 21789236, 2011).